FGF21 (fibroblast growth factor 21)
Diseases named in the same sentence as FGF21 in open-access papers (continued):
Sharing a sentence is not in itself a finding about the gene and the disease.
depression (continued). "Here, we mainly concentrated on the reported depression-related FGF system members, including FGFR1, FGF2, FGF9, FGF21, and FGF22." (PMID 30804785, 2019). "Correlation analysis between FGF19 and FGF21 levels and RBANS in depression." (PMID 37266540, 2023). "FGF21 stimulates the expression of the hormone CRH, and the increased concentration of CRH contributes to the etiology of disorders such as anorexia nervosa, obsessive-compulsive disorder, anxiety, and depression." (PMID 37999598, 2023). "Using data from the EMBARC study, FGF21 was found to be higher in those with MDD compared to HC and FGF21 remained relatively stable over time and was not impacted by depression severity or by treatment." (PMID 35017468, 2022). "A negative correlation between cerebrospinal fluid FGF21 level and depression scores has also been reported." (PMID 34472154, 2021). "However, few studies have highlighted the antidepressant effects of FGF21 on lipopolysaccharide (LPS)-induced mice, and the anti-inflammatory mechanism of FGF21 in depression has not yet been elucidated." (PMID 32184729, 2020). "Selection of FGF21 as a metabolic biomarker of interest may not be adequate to fully understand the interplay between metabolic biomarkers and depression symptoms, in particular given that weight likely plays an important role in metabolic markers, as evidenced by the results." (PMID 35017468, 2022). "Compared to individuals without depression, those with depression had a higher fat mass index (FMI (β = 0.48, 95% CI 0.22–0.74)) and increased blood levels of fibroblast growth factor 21 and Interleukin-6 in early adulthood." (PMID 39523673, 2024).
ischemia (17 papers, 2014 to 2025). A hypoperfusion of the BLOOD through an organ or tissue caused by a PATHOLOGIC CONSTRICTION or obstruction of its BLOOD VESSELS, or an absence of BLOOD CIRCULATION. "FGF21 is potentially involved in modulating astrocyte-mediated inflammation and cell migration after ischemia." (PMID 40021824, 2025). "Our findings reveal that FGF21 is a key modulator of astrocyte reactivity and participates in controlling the severity of neuroinflammation and brain injury after ischemia." (PMID 40021824, 2025). "Balance scores revealed that the MND + FGF21 group had the best neurological recovery following ischemia, while the MHFD group had the worst neurological function after cerebral infarction, and the other two groups were in between." (PMID 35096806, 2021). "Behavioral data from days 1–3 and MRI data from Day 3 showed rats treated with FGF21 following ischemia had better neurological function recovery than untreated rats." (PMID 35096806, 2021). "In case 2, a severe increase of FGF‐21 was seen during hemorrhagic shock, which indicates that other factors, such as ischemia impair mitochondrial function as well." (PMID 32071844, 2020). "Collectively, our data suggest that pemafibrate can promote revascularization in response to ischemia, at least in part, by its ability to promote endothelial cell function through direct and FGF21-mediated activation of eNOS in endothelial cells." (PMID 32584895, 2020). "FGF-21 mRNA levels were also dramatically decreased in both cortex and striatum on Day 3 after ischemia." (PMID 26790818, 2016). "Inhibition of PI3K/Akt, AMPK, ERK1/2 and ROR-α (retinoic-acid receptor alpha) pathway led to significant decrease of FGF21 induced cardio-protection and restoration of cardiac function in response to global ischemia." (PMID 24498293, 2014). "In lean hearts, there was a maximum increase in cardiac secreted FGF21 levels following 30 mins reperfusion (post ischemia) [P<0.001 30 mins vs 0 min reperfusion]." (PMID 24498293, 2014). "Thus, it is likely that pemafibrate stimulates revascularization process after ischemia through at least two mechanisms: direct modulation of endothelial cell behavior and enhancement of pro-angiogenic factor FGF21-mediated endothelial cell function." (PMID 32584895, 2020). "Our results showed that FGF-21 protein levels were markedly reduced in the ischemic cortex and striatum, and that these reductions were restored by TubA treatment, especially in the cortex on Day 3 after ischemia." (PMID 26790818, 2016). "Interestingly, FGF21 infusion did not improve cardiac function and/or reduce infarct size in obese rat hearts following global ischemia, despite increased production and secretion of FGF21 in these obese rat hearts." (PMID 24498293, 2014). "Thus, we determined the cell sources of cerebral FGF21 in the pathological context of ischemia." (PMID 40021824, 2025). "Therefore, we postulate the existence of preformed FGF21 protein secretory granules which could account for the acute release of FGF21 from the heart following global ischemia." (PMID 24498293, 2014). "In conclusion, the changes in FGF-19 and FGF-21 levels in blood reflect their potential roles among patients after transplantation/ FGF-19 may have a protective effect on the graft during the period of ischemia and subsequent reperfusion, whereas FGF-21 seems to enhances hepatocyte regeneration." (PMID 40648894, 2025). "Using MCAO and in vitro ischemia models, we showed that LINC00894 stabilized EIF5 to enhance the expression of ATF4, which transcriptionally regulated the expression of FGF21 and ACOD1, thus protecting cells from brain ischemia-induced damage." (PMID 39060766, 2024). "Based on these findings, we believed that AAV-mediated ectopic expression of LICN00894 could affect FGF21 and ACOD1 expression, through which the protective effect against ischemia-induced brain injury is exercised." (PMID 39060766, 2024).
ischemic stroke (16 papers, 2019 to 2025). A stroke disorder caused by obstruction of blood flow to the brain, due to thrombotic (local blood clot formation) or embolic (due to a blood clot or other material traveling from another site) event. "Recent studies showed FGF21 levels are elevated in ischemic stroke and associated with poor prognosis." (PMID 38789571, 2024). "The correlation between FGF21 and the incidence of ischemic stroke exhibited a positive association." (PMID 38789571, 2024). "Higher serum FGF21 levels were negatively associated with visual acuity improvement (P = 0.029, OR [95%CI] = 0.466[0.235, 0.925]) and positively correlated with concurrent ischemic stroke (P = 0.04, OR [95% CI] = 1.944[1.029, 3.672]) in RAO patients." (PMID 38789571, 2024). "Our study presents a novel, Salmonella - based platform for targeted and sustained FGF21 delivery, offering a promising therapeutic strategy for ischemic stroke with robust efficacy and minimal systemic toxicity." (PMID 40581646, 2025). "The vasculoprotective action of FGF21 has been well demonstrated in preclinical models of aging, atherosclerosis, ischemic stroke and traumatic brain injury (TBI)." (PMID 40407975, 2025). "Overexpression of FGF21 dramatically improved the therapeutic efficacy of MSCs in treating ischemic stroke." (PMID 40581646, 2025). "This makes FGF21 a more suitable candidate for promoting comprehensive neural repair after ischemic stroke." (PMID 40581646, 2025). "Multivariable logistic regression analyses were performed to evaluate the significance of FGF21 in assessing the risk of developing RAO and its impact on vision and concurrent ischemic stroke." (PMID 38789571, 2024). "FGF21 can protect against BBB disruption by activating PPARγ after ischemic stroke in T2DM db/db mice." (PMID 36594101, 2023). "Our study shows the association of FGF21 and RBM3 on the prognosis of ischemic stroke patients, and supports the development of new pharmacological tools for RBM3-mediated neuroprotection in the absence of hypothermia." (PMID 35207221, 2022). "Therefore, bacterial-induced secretion of FGF21 is effective in maintaining the integrity of the cerebral cortex and reducing cortical atrophy in the chronic phase after ischemic stroke, with long-term effectiveness." (PMID 40581646, 2025). "Notably, our results are consistent with a prior investigation that highlighted FGF21 as a promising anti-inflammatory agent in ischemic stroke." (PMID 38720350, 2024). "FGF21 serves as a neuroprotectant with cognition-enhancing effects; it can inhibit neuroinflammation following ischemic stroke and maintain blood–brain barrier integrity in an ischemic stroke model." (PMID 39060766, 2024). "Our study found that high levels of FGF21 were positively correlated with the incidence of ischemic stroke in RAO patients, suggesting that FGF21 levels hold promise as both a predictive marker and a potential therapeutic target for concurrent ischemic stroke management in RAO." (PMID 38789571, 2024). "Elevated serum FGF21 levels could promote the development of RAO and indicate worse visual prognosis and increase the risk of concurrent ischemic stroke, which might help clinicians early diagnose and treat RAO patients." (PMID 38789571, 2024). "In addition, circulating FGF21 was increased in response to cardiac stress, ischemic stroke, limb ischemia/reperfusion injury, and toxic kidney injury." (PMID 37218012, 2023). "Thus, FGF21 is a critical growth factor that modulates astrocyte reactivity and may be a potential therapeutic target for treating ischemic stroke." (PMID 40021824, 2025). "In conclusion, our study emphasized that FGF21 could serve as a potential biomarker for the occurrence of RAO, but also highlighted the association between elevated FGF21 levels and worse visual outcomes and risk of concurrent ischemic stroke." (PMID 38789571, 2024). "Furthermore, our experiments showed that FGF21 is neuroprotective in ischemic stroke." (PMID 35096806, 2021).
ischemic stroke (continued). "FGF21 may be developed into a new and powerful approach to treat ischemic stroke." (PMID 35096806, 2021). "FGF21’s multimodal mechanisms (neuroprotection, anti-inflammation, metabolism) and favorable safety profile make it superior to single-target growth factors (e.g., BDNF, VEGF) for ischemic stroke therapy." (PMID 40581646, 2025). "This study verified bacterially secreted FGF21 reduced neural apoptosis after dMCAO by activating autophagy through its action on neuronal FGFR1 receptors, reduced infarct foci size, and improved neurological function in ischemic stroke mice." (PMID 40581646, 2025).
lipodystrophy (16 papers, 2011 to 2025). A congenital or acquired disorder characterized by abnormal loss or redistribution of the adipose tissue in the body. "In the present investigation, our overarching goal was to explore the potential of FGF21/sTGFBR2 gene therapy in improving lipodystrophy-associated metabolic dysfunction." (PMID 40663389, 2025). "Taken together, combination gene therapy of FGF21 and sTGFBR2 has the potential to improve metabolic conditions associated with lipodystrophy." (PMID 40663389, 2025). "Especially in those with lipodystrophy or MetSyn, these changes are accompanied by increased levels of stress‐associated hormones such as FGF21." (PMID 35510313, 2022). "Elevated FGF-21 levels have also been described in patients with HIV-associated lipodystrophy, where atypical FDG fat distribution is also described." (PMID 22214514, 2011). "Lipodystrophy is associated with upregulation of Fgf21 (encoding fibroblast growth factor 21)." (PMID 40709262, 2025). "Then, we evaluated whether FGF21 alone or FGF21/sTGFBR2 combination therapy improved metabolic dysfunction associated with lipodystrophy in an adipocyte-specific lamin A/C–knockout (LmnaADKO) mouse model." (PMID 40663389, 2025). "Thus, metabolic dysfunction caused by lipodystrophy is improved by targeting FGF21 and TGFB signaling, but effectiveness in preclinical models may be dependent upon environmental temperature and presence of adipose tissue." (PMID 40663389, 2025). "In this model of lipodystrophy, an FGF21 analog, LY2405319, improved insulin sensitivity in young mice housed at 22°C." (PMID 40663389, 2025). "We therefore sought to further explore correlations of FGF21 with the lipodystrophy phenotype and other adipokines in our cohort." (PMID 38271099, 2024). "In supporting this point of view, previous reports have shown significantly increased plasma FGF21 in lipodystrophy mice and humans as well as diabetic patients." (PMID 37479751, 2023). "We observed remarkably similar alterations in the circulating parameters of cohorts representing PLWH with lipodystrophy and elderly individuals, including mild increases in insulin resistance and increased levels of proinflammatory cytokines and FGF21." (PMID 35300561, 2022). "Other studies performed in animals, particularly in rats, have also found elevated FGF21 protein levels and an overexpression in T2D, IR and lipodystrophy models." (PMID 34019585, 2021). "In fact normal FGF21-induced signaling is observed in ob/ob adipose, whereas we observe impaired FGF21 signaling in lipodystrophy WAT." (PMID 22792234, 2012). "Upregulation of FGF21 could be considered a compensatory mechanism, yet it is insufficient to alleviate the metabolic consequences of lipodystrophy." (PMID 41465464, 2025). "To investigate whether metabolic improvements observed in obese mice with FGF21/sTGFBR2 are also observed with lipodystrophy, we studied LmnaADKO lipodystrophic mice in which Lmna is knocked out of adipocytes." (PMID 40663389, 2025). "Furthermore, FGF21 plasma levels have been proposed as a marker for the following lipodystrophy in human immunodeficiency virus (HIV)-positive patients." (PMID 37479751, 2023). "Additionally, the visceral adipose mass in OVX+FGF21 LKO mice was even numerically lower than in sham controls, suggesting FGF21 LKO caused a lipodystrophy of visceral adipose in mice." (PMID 37834368, 2023). "In PLWH with symptoms of lipodystrophy, serum FGF21 appears increased." (PMID 34019585, 2021). "To delineate if adipose tissue is the predominant organ responsible for anti-diabetic effects of FGF21, we treated mice with reduced body fat (lipodystrophy mice with adipose specific expression of active sterol regulatory element binding protein 1c; Tg) with recombinant murine FGF21 (rmuFGF21)." (PMID 22792234, 2012). "Serum FGF21 levels are increased in HIV-1-infected patients with lipodystrophy." (PMID 21331285, 2011).
lipodystrophy (continued). "We observed widespread transcriptomic changes in response to lipodystrophy in this study, with 1,953 differentially expressed genes between vehicle-treated lipodystrophic and control livers and 888 genes that differed between FGF21-treated lipodystrophic and control livers." (PMID 40663389, 2025). "Taken together, these experiments suggest that targeting FGF21 and TGFB1 may have utility for treatment of metabolic dysfunction associated with lipodystrophy and that murine housing temperature is an important variable to consider when studying therapeutic metabolic endpoints." (PMID 40663389, 2025). "We hypothesized that muscle FGF-21 mRNA would be altered in HIV patients with lipodystrophy." (PMID 23533568, 2013). "Gene therapy with targets such as FGF21 and soluble TGF-β receptor 2 (sTGFBR2) provides an alternative approach, specifically in lipodystrophy." (PMID 40663389, 2025). "Recently, circulating FGF-21 was observed in HIV-infected patients, and especially those with lipodystrophy." (PMID 23533568, 2013). "Given the unmet clinical need for patients with LMNA-induced lipodystrophy, we designed this study to explore the impact of a gene treatment using viral mediated delivery of FGF21 and sTGFBR2 in a preclinical model of LMNA-induced lipodystrophy created in our lab." (PMID 40663389, 2025). "Plasma TAG concentrations were elevated by lipodystrophy, but FGF21/sTGFBR2 did not decrease TAG concentrations in fed lipodystrophic mice 12 weeks posttreatment." (PMID 40663389, 2025).
central obesity (14 papers, 2019 to 2023). "To further understand the underlying mechanisms by which FGF21 LKO abrogated OVX-induced central obesity in female mice, we profiled the transcriptome of visceral adipose tissues." (PMID 37834368, 2023). "Central obesity was associated with increased Klotho levels [156.4 pg/ml vs 118.5 pg/ml, p = 0.0275] and FGF21 levels [93.0 pg/ml vs 70.1 pg/ml, p = 0.0193] as well as a decrease in FGF19 levels [160.6 pg/ml vs 229.4 pg/ml, p = 0.0264]." (PMID 32546231, 2020). "In conclusion, men with central obesity and lower circulating FGF21 may benefit more than others in terms of weight loss obtained following this diet." (PMID 36761216, 2023). "Men with central obesity and lower circulating FGF21 may benefit more than others in terms of weight loss obtained following this diet." (PMID 36761216, 2023). "Accordingly, we hypothesize that the increase of circulating FGF21 is an important causative factor for the development of central obesity in estrogen-depleted females via promoting GC production." (PMID 37834368, 2023). "Correlation analysis showed a significant positive association of serum FGF21 levels with body shape parameters, including weight, waistline, BMI, ABSI, abdominal obesity, and TG, respectively (all p < 0.05)." (PMID 37424900, 2023). "All these results strongly demonstrate that liver-derived FGF21 plays an essential role in mediating OVX-induced central obesity by promoting high GC production." (PMID 37834368, 2023). "In summary, liver-derived FGF21 plays an essential role in mediating the development of central obesity in OVX mice by promoting GC production." (PMID 37834368, 2023). "Accordingly, we suggested that the liver FGF21-adrenal GCs-visceral adipose 11β-HSD1 signaling cascade plays a central role in mediating OVX-induced central obesity." (PMID 37834368, 2023). "Collectively, our results suggest that liver FGF21 plays an essential role in mediating OVX-induced central obesity by promoting GC production." (PMID 37834368, 2023). "Consistent with the change of FGF21, a higher prevalence of abdominal obesity was observed in these individuals." (PMID 37424900, 2023). "As expected, serum FGF21 levels were significantly associated with weight, waistline, BMI, ABSI, and abdominal obesity; the positive correlation remained highly significant when adjusted for age and T2DM duration." (PMID 37424900, 2023). "In conclusion, weight loss and concomitant health improvements upon a 12-week 25% ER diet were not accompanied by changes in fasting or postprandial plasma FGF21 levels in middle-aged individuals with abdominal obesity." (PMID 36501091, 2022). "In the univariate logistic analyses, mitochondrial stress biomarkers correlated with liver fat content with a high significance coefficient (Wald χ2; 42.2 for FGF21, p <0.001), in addition to central obesity (Wald χ2; 43.5 for WHR, p <0.001)." (PMID 35663311, 2022). "This group included 42 (62%) individuals who met the criteria for abdominal obesity, compared to the low FGF21 group, n = 27 (40%)." (PMID 33670024, 2021). "It seems that FGF21, FGF19 and β-klotho concentrations are correlated with risk factors for metabolic diseases especially in subjects with abdominal obesity." (PMID 31151464, 2019). "Accordingly, mild suppression of hyper-FGF21 without unfavorable insulin-associated metabolic changes should be an interesting strategy to prevent or treat OVX/menopause-caused central obesity." (PMID 37834368, 2023). "To see whether the abrogative effects of FGF21 LKO on OVX-induced central obesity were realized via altering FSH and/or corticosterone levels in female mice, we quantified their concentrations in serum using ELISA." (PMID 37834368, 2023). "The increased FGF21 concentrations observed in children and adolescents with MS may be an effect of the FGF21 resistance observed in subjects with central obesity." (PMID 32546231, 2020).